ALB (albumin)
Diseases named in the same sentence as ALB in open-access papers (continued):
Sharing a sentence is not in itself a finding about the gene and the disease.
skin cancer (9 papers, 2014 to 2024). "In this study, doxorubicin was loaded in a chitosan–albumin nanogel with the aim of improving its stability and exploring the potential of the system in the treatment of skin cancer." (PMID 38399401, 2024). "Here, chitosan-based hydrogels containing albumin spheres and Aloe vera juice, designed for the treatment of skin cancers or burn wounds resulting from radiotherapy, were developed." (PMID 34640229, 2021). "The impact of albumin on the prognosis of skin cancer was evident." (PMID 39464703, 2024). "Thus, the loading of doxorubicin into the developed chitosan–albumin nanogel definitely stabilized the drug against photodegradation and increased its antineoplastic effect on the skin cancer cell line." (PMID 38399401, 2024). "Among adverse events, correlational analyses suggested that gastrointestinal symptoms, rash and skin cancer may be related to each other, while uric acid reduction, albumin reduction and infection formed a cluster." (PMID 26064192, 2015). "In the present study, we developed bovine serum albumin (BSA)-coated silver NPs (BSA-Silver NPs) and characterized in vitro multimodal therapeutic activities of NPs for the treatment of skin cancer." (PMID 33920666, 2021).
thyroid (9 papers, 2016 to 2025). "Serum urea, creatinine, electrolytes, albumin, lipid profile, and thyroid function tests, including thyroid-stimulating hormone (TSH), free triiodothyronine (fT3), and free thyroxine (fT4), were measured using an electrochemiluminescence immunoassay (ECLIA)." (PMID 41552179, 2025). "Thyroid disorders are known to hinder albumin synthesis, promote bone resorption and impede bone repair, leading to reduced bone mass and increased bone fragility." (PMID 41041308, 2025). "Furthermore, a multivariate logistic regression analysis was conducted including age, super-refractory SE, abnormal thyroid function, STESS, red blood cell count, red cell distribution width, platelet count, albumin, FT3 and TSH." (PMID 39583963, 2024). "The prevalence of men, patients with concomitant thyroid disorders, patients with symptoms concerning bone involvement, abdominal, cardiovascular and neurological symptoms, and values of pre-operative intact PTH and albumin-corrected calcium were higher in the PC group than in the APT one." (PMID 37834940, 2023).
acute lung injury (8 papers, 2019 to 2025). A condition of lung damage that is characterized by bilateral pulmonary infiltrates (pulmonary edema) rich in neutrophils, and in the absence of clinical heart failure. "Previous studies by our group have demonstrated that megalin, an endocytic receptor, plays a key role in the uptake of albumin from the alveolar space, and that albumin clearance is significantly reduced in acute lung injury (ALI)." (PMID 37727782, 2023). "Our findings, in which HS did not limit endothelial or organ injury when added to Ringer’s lactate or albumin resuscitation, were in contrast to a previous study in a histone-induced acute lung injury mouse model, wherein HS attenuated lung injury." (PMID 37892576, 2023). "Increased miR-150 decreases neutrophil counts and production of inflammatory cytokines IL-1β, IL-6, and TNF-α along with levels of total protein, albumin and IgM in the BAL fluid in LPS-induced acute lung injury mice in vivo, as well as alleviating LPS-induced A549 cell apoptosis in vitro." (PMID 32315984, 2020).
Alkalosis (8 papers, 2013 to 2025). Depletion of acid or accumulation base in the body fluids. "The biochemical consequence of this alkalosis is a complex shift in the distribution of plasma ions: the rise in pH enhances the binding affinity of albumin for calcium, leading to a rapid reduction in ionized calcium levels." (PMID 40981011, 2025). "Subjects experiencing acute respiratory alkalosis showed elevated hemoglobin, albumin, and total calcium levels, likely due to hyperventilation causing a reduced intravascular volume." (PMID 39666120, 2024). "The most likely cause of the observed progressive decline in capillary blood ionized calcium seems alkalosis, conducive to increased binding of calcium to albumin." (PMID 24002469, 2013). "Within the modern approach, the lack of albumin led to an Atot-alkalosis." (PMID 30650142, 2019).
bacterial meningitis (8 papers, 2010 to 2026). Inflammation of the membranes surrounding the brain and spinal cord due to a bacterial infection. "During bacterial meningitis, destruction of the blood-brain barrier is related to disease progression and is reflected by increased brain albumin levels." (PMID 28086930, 2017). "In addition to the direct culture of bacteria from CSF, the presence of nucleated leukocytes and lowered levels of glucose and albumin are important CSF markers used for diagnosis of bacterial meningitis." (PMID 39887961, 2025). "Unexpectedly, our bacterial meningitis patients possessed PGRN levels that were positively correlated with numbers of nucleated leukocytes and albumin levels and negatively correlated with glucose." (PMID 39887961, 2025).
Candidemia (8 papers, 2009 to 2025). A form of invasive candidiasis where species of CANDIDA are present in the blood. "Serum albumin levels are also important factors that affect bloodstream infections in hospitals and are associated with increased mortality from candidemia." (PMID 32795259, 2020). "Five independent factors included Candida albicans, decreased albumin, multiple organ dysfunction syndrome, solid tumor and septic shock were adopted in a nomogram for 30-days mortality of candidemia." (PMID 39963405, 2025). "The finding that both albumin levels and disease state were significant covariates in the population PK model is likely to be related, as, in general, albumin levels were reduced in subjects with hepatic impairment as well as in subjects infected with candidemia and/or invasive candidiasis." (PMID 38014945, 2023). "To enhance the clinical applicability of the mSOFA_3 model in predicting mortality in candidemia, we transformed lactate, BUN, and albumin values into scores ranging from 0 to 4 based on clinical significance, reflecting severity." (PMID 40593023, 2025). "Together, albumin, lactate, and BUN provide an integrated view of both metabolic and inflammatory disturbances in candidemia patients." (PMID 40593023, 2025). "The covariate analysis demonstrated that disease state (defined as candidemia and/or invasive candidiasis patients and hepatically impaired subjects), BSA, and serum albumin are significant predictors of variability in the PK of rezafungin." (PMID 38014945, 2023). "The patients with candidemia and/or invasive candidiasis who participated in the STRIVE and ReSTORE studies were, in part, critically ill, which probably explains their lower levels of serum albumin." (PMID 38014945, 2023). "The systematic search revealed the following statistically significant predictors of PK variability: albumin on V23; BSA on CL, V1, and V23; and disease status (defined as candidemia and/or invasive candidiasis patients and hepatically impaired subjects) on CL and V1." (PMID 38014945, 2023).
complication (8 papers, 2015 to 2025). Any disease or disorder that occurs during the course of, or because of, another disease, treatment, or procedure. "These processes significantly alter the structures and functions of plasma proteins, particularly serum albumin, which plays a crucial role in the pathogenesis of diabetic vascular complications." (PMID 41226224, 2025). "This implies that serum albumin might contribute to the development of diabetic chronic vascular complications through its antioxidant, anti-inflammatory and anticoagulant effects." (PMID 31427625, 2019). "Women with pre-eclampsia without end-organ complications had a 1.5-fold increased albumin ratio compared to normotensive controls (95% CI 1.17–1.98)." (PMID 40344719, 2025).
conjunctivitis (8 papers, 2019 to 2025). Inflammation of the conjunctiva of the eye. "Re-examination of two dogs following therapy of the underlying ocular disease (cases #12–13) showed reduction in lacrimal albumin concentrations concomitant with a reduction in the conjunctivitis score." (PMID 31354477, 2019). "Lacrimal albumin levels were also increased in 13 dogs with naturally acquired conjunctivitis, up 2.7–14.9 fold compared to contralateral healthy eyes." (PMID 31354477, 2019). "Leakage of serum albumin in tear fluid of eyes with conjunctivitis suggests a breakdown of the blood–tear barrier." (PMID 31354477, 2019). "As a proof of concept, our study examined 13 dogs with naturally acquired conjunctivitis and confirmed the presence of elevated albumin levels in tears of affected eyes." (PMID 31354477, 2019). "Total protein content and serum albumin levels increase after histamine administration, as are lacrimal albumin levels during naturally acquired conjunctivitis; lacrimal albumin concentration decreases in parallel with the reduction in the conjunctivitis score." (PMID 34439851, 2021). "In our case study, a 12-year-old boy exhibited persistent fever, bilateral non-purulent conjunctivitis, edematous limbs, unresponsive shock, low levels of albumin, significantly elevated levels of CRP." (PMID 39093792, 2024).
diffuse large B-cell lymphoma (8 papers, 2017 to 2024). "Objectives and study design: In this population-based study of 602 patients, we amended C-reactive protein (CRP) and plasma albumin (PA) levels around the diagnosis of diffuse large B-cell lymphoma (DLBCL) to the International Prognostic Index (IPI) and assessed 0–90, 91–365, and +365-day survival." (PMID 35238275, 2022). "Albumin is a significant predictor of survival in patients with diffuse large B-cell lymphoma." (PMID 35892082, 2022). "The prognostic value of albumin changes between diagnosis and end-of-treatment (EoT) in diffuse large B-cell lymphoma (DLBCL) remains unknown." (PMID 33585232, 2020).
Disseminated intravascular coagulation (8 papers, 2012 to 2024). Disseminated intravascular coagulation is characterized by the widespread activation of coagulation, which results in the intravascular formation of fibrin and ultimately thrombotic occlusion of small and midsize vessels. "Impaired albumin levels disrupt coagulation factor transport, increasing the risk of bleeding and disseminated intravascular coagulation (DIC)." (PMID 39539863, 2024). "The 14-day mortality rate, albumin level, and the number of patients with disseminated intravascular coagulation (DIC) were also assessed." (PMID 32778146, 2020). "Univariate analysis showed that disseminated intravascular coagulation (DIC) score > 5 (p = 0.001), albumin < 25 g/L (p = 0.000), HGB < 60 g/L (p = 0.001), and platelet count (PLT) < 30 × 109/L (p = 0.042) correlated with prognosis." (PMID 31783813, 2019).
Hodgkins lymphoma (8 papers, 2013 to 2025). A heterogeneous group of malignant lymphoid neoplasms of B-cell origin characterized histologically by the presence of Hodgkin and Reed-Sternberg (HRS) cells in the vast majority of cases. "Although at 87.1%, the PPV of albumin in Hodgkin lymphoma is lower, the other PPVs, which range between 93.4% and 100%, as well as the completeness, ranging between 98.1% and 100%, are high." (PMID 27336800, 2016). "In two homozygous E1-DN mice with the highest albumin excretion, the mesangial matrix accumulation was classified as focal, global nodular sclerosis by an expert pathologist who examined the samples blinded from the genotypes." (PMID 26000279, 2015). "Further, we found that LMR was associated with Ann Arbor stage, IPI score, ECOG performance status, extranodal sites of disease, serum LDH level and B symptom in DLBCL, and with Ann Arbor stage, stage, IPS, WBC count, albumin level and hemoglobin level in Hodgkin's lymphoma." (PMID 26942464, 2016). "Regarding predictive factors for Hodgkin's lymphoma, low LMR was significantly associated with high white blood cell count (HR: 0.67, 95% CI: 0.46–0.99; P = 0.047), low albumin (HR: 0.47, 95% CI: 0.36–0.60; P < 0.001) and low Hemoglobin (HR: 0.41, 95% CI: 0.30–0.56; P < 0.001)." (PMID 26942464, 2016).
infarction (8 papers, 2012 to 2024). A localised pathological necrosis of tissue resulting from obstruction of the blood supply usually by a thrombus, an embolus, or vascular torsion. "In a mouse model of AIS, a low-dose local arterial infusion of 20% human serum albumin solution was shown to significantly reduce the cerebral infarct volume and alleviate the neurological dysfunction caused by middle cerebral artery occlusion." (PMID 39403266, 2024). "A low-dose local arterial infusion of 20% human serum albumin solution can quickly and safely achieve a high drug concentration in the infarction area, producing a greater neuroprotective effect." (PMID 39403266, 2024). "Patients with a higher NIHSS score, a more elevated mRS, a bigger infarction volume, and increased albumin levels experienced worse outcomes." (PMID 38846203, 2024). "Much researches have shown that ALB administration could effectively reduce infarction volumes and brain edema, as well as BBB permeability." (PMID 33314645, 2021). "According to the current study results, most patients with a positive outcome had decreased mRS scores, albumin levels, NIHSS scores, and infarction volume." (PMID 38846203, 2024). "Therefore, serum albumin levels do not exclusively influence the patient's prognosis; the size of the infarction also significantly influences it." (PMID 38846203, 2024).
monoclonal gammopathy (8 papers, 2015 to 2026). A condition characterized by the abnormal presence of monoclonal immunoglobulins in the blood or urine. "The presence of red flags such as proteinuria, low serum albumin, and monoclonal gammopathy should prompt thorough diagnostic workup." (PMID 41493762, 2026). "Diagnostic accuracy of gamma gap, albumin-to-globulin ratio, and multivariable logistic regression models for predicting monoclonality in patients evaluated for monoclonal gammopathy at a tertiary hospital laboratory in South Africa from 01 September 2015 to 30 September 2022." (PMID 40183108, 2025). "The chemistry profile of FCGS individuals exhibits a high value of total protein (hyperglobulinemia), which is attributed to elevated levels of albumin, globulin, and monoclonal gammopathy (alpha 1 and 2, beta, and gamma 1 and gamma 2)." (PMID 41019092, 2025). "According to the results of previous studies, albumin-corrected calcium cannot completely and comprehensively correct pseudohypercalcemia in patients with monoclonal gammopathy." (PMID 39544294, 2024). "As a result, the use of the traditional albumin-corrected calcium formula in patients with monoclonal gammopathy) was restricted." (PMID 39544294, 2024). "In our patient, the association between progressive edema, severe hypotension with multiple organ dysfunction, inspissatio sanguinis with elevated hematocrit, decreased albumin levels, rhabdomyolysis, and monoclonal gammopathy finally addressed to the diagnosis." (PMID 25738482, 2015). "An elevated gamma gap (>4 g/dL), the difference between serum total protein and albumin, can trigger testing for chronic infections or monoclonal gammopathy, despite a lack of evidence supporting this clinical threshold." (PMID 31940353, 2020). "Furthermore, we classified the patients with monoclonal gammopathy according to the International Staging System (ISS) and Revised ISS, based on their serum levels of albumin, β2 microglobulin, and lactate dehydrogenase (LDH), and the presence of high-risk chromosomal abnormalities (CA)." (PMID 37629268, 2023).
Myocardial fibrosis (8 papers, 2015 to 2025). "Existing evidence indicates that the ALB concentration is associated with myocardial fibrosis, adverse pulsatile aortic hemodynamics, and prognosis in patients with HFpEF." (PMID 39781528, 2025). "Monitoring albumin may offer a simple biomarker for identifying patients at higher risk of myocardial fibrosis in AS." (PMID 40142874, 2025). "In the pathological process of myocardial fibrosis after MI, we first used human serum albumin-carried collagenase I (HSA-C) to degrade fibrotic collagen and reduce contrast agent retention in the cardiac fibrosis." (PMID 38666825, 2024). "Lower albumin could be a marker of myocardial fibrosis and could be a marker of the atrial fibrosis in patients with AF." (PMID 36615064, 2022). "An inverse relationship between serum albumin and ECV was observed, with lower albumin levels correlating with higher ECV and increased myocardial fibrosis (r = −0.7; p < 0.001)." (PMID 40142874, 2025).
Pancytopenia (8 papers, 2016 to 2024). An abnormal reduction in numbers of all blood cell types (red blood cells, white blood cells, and platelets). "His liver function (total bilirubin, albumin, and prothrombin time) and pancytopenia improved during the 5 years postoperatively." (PMID 38647617, 2024). "Complete blood count was suggestive of pancytopenia with hemoglobin of 10.8 g/dL, total white cell count 3.36 (1000/uL) (absolute neutrophil count 490 micro/L), platelets 19,000, serum albumin 3.1 g/dL, ESR elevated at 83 mm/hr, CRP elevated at 86.6 mg/L, and ferritin mildly elevated at 625 ng/mL." (PMID 38523896, 2024). "As pancytopenia can be a late manifestation, elevation of urea, creatinine, aminotransferases, and albumin as well as electrolytes disturbances may result in MTX associated liver and renal side effects." (PMID 32850138, 2020). "Non-use of folic acid supplements and serum albumin levels were significantly associated with the severity of pancytopenia (non-severe versus severe: 57.9% versus 8.3%, p = 0.008; 3.1 g/dl versus 2.3 g/dl, p = 0.001, respectively)." (PMID 27128679, 2016). "AR and ITBL patients also displayed pancytopenia, and lower LYM, lower liver synthesis function markers (ALB and FIB), but higher ITBL and PT, compared to the healthy controls." (PMID 32530819, 2020). "Like severe pancytopenia, non-use of supplemental folic acid and serum albumin levels were the significant factors affecting the disease severity (non-severe versus severe: 66.7% versus 18.8%, p = 0.007; 3.2 g/dl versus 2.5 g/dl, p = 0.003, respectively)." (PMID 27128679, 2016).
pericarditis (8 papers, 2016 to 2025). An inflammatory process affecting the pericardium. "Although there was no statistical significance in serum albumin levels, the serum albumin/globulin ratios showed significantly lower results in the HIV-uninfected TB pericarditis group." (PMID 27899066, 2016). "This study aimed to evaluate the prognostic significance of the Pan-Immune-Inflammatory Value (PIV) and the hemoglobin, albumin, lymphocyte, and platelet (HALP) score in predicting disease severity, recurrence, and prognosis in patients with acute pericarditis." (PMID 40958325, 2025).
Tricuspid regurgitation (8 papers, 2019 to 2026). Failure of the tricuspid valve to close sufficiently upon contraction of the right ventricle, causing blood to regurgitate (flow backward) into the right atrium. "Lower serum albumin predicted higher risk of tricuspid regurgitation velocity ≥ 2.5 m/s (OR = 1.1 per g/L, P ≤0.01)." (PMID 32776978, 2020). "In addition, the MELD-albumin score was useful in risk stratification and patient selection for patients with tricuspid regurgitation (TR) prior to ITVR." (PMID 35845070, 2022). "However, heart valve diseases (i.e. aortic valve stenosis and mitral or tricuspid regurgitation) were more prevalent in patients with lower albumin levels (p ≤ .030 for all three comparisons)." (PMID 41452958, 2026). "Recently, a new MELD-Albumin score including albumin to replace INR in the conventional MELD score has been investigated in patients undergoing tricuspid annuloplasty for severe tricuspid regurgitation revealing to be a prognostic indicator as good as the MELD-XI score." (PMID 33490119, 2020).